MDM2 (MDM2 proto-oncogene)
Diseases named in the same sentence as MDM2 in open-access papers (continued):
Sharing a sentence is not in itself a finding about the gene and the disease.
cancer (continued). "In conclusion, Mdm2 overexpression can promote cancer cell resistance to DNA-damaging agents and limit the effectiveness of chemotherapeutic drugs." (PMID 15026814, 2004). "Of these 3’UTRs, we focused on MDM2 given its role in cancer." (PMID 40381037, 2025). "As these strategies mature, MDM2 inhibition may yet fulfill its potential as a transformative cancer therapy, but only through careful attention to the biological contexts that determine its therapeutic index." (PMID 41170373, 2025). "Consequently, targeting this crosstalk through the combined inhibition of AKT/mTOR and MDM2 has emerged as a promising therapeutic strategy in cancers exhibiting excessive activation of this pathway." (PMID 41515979, 2025). "Thus, together with our SILAC data, the chromatin fractionation and immunofluorescence analyses pointed to a role for MDM2 in regulating 53BP1 recruitment to chromatin in cancer cells." (PMID 40626562, 2025). "Finally, we describe potential therapeutic approaches targeting both MYCN and MDM2 for the treatment of MYCN-driven cancer." (PMID 39802403, 2025). "MDM2 is overexpressed in cancer cells in 7% of all malignancies." (PMID 40191734, 2025). "Notably, the membrane protein E-cadherin (CDH1), which mediates homotypic cell–cell interactions and modulates epithelial–mesenchymal transition, a key feature of tumorigenesis–metastasis and cancer progression, is a substrate for MDM2." (PMID 39960347, 2025).
cancer (continued). "This review examines the impact of the Mdm2/MdmX lid on ligand binding, providing valuable insights for future research and guiding new approaches to the screening and design of innovative anti-cancer therapeutics." (PMID 40427535, 2025). "Among DUBs, USP7 stabilizes Mdm2 and represents an emerging target for cancer therapy." (PMID 40295432, 2025). "Murine double minute 2 (MDM2) is involved in various cancers and is an attractive target." (PMID 40508092, 2025). "Furthermore, it was shown that increased MDM2 levels encouraged the ubiquitination and degradation of E-Cadherin, consequently, hastening the aggressiveness of cancer cells." (PMID 40308267, 2025). "Furthermore, supporting the cancer-specific nature of this editing, MDM2 RNA editing was less prevalent in normal breast tissue." (PMID 40381037, 2025). "Although the main focus has been on cancer risk, there have also been numerous studies assessing the impact of MDM2 polymorphisms on non-malignant phenotypes." (PMID 39979836, 2025). "Interestingly, the other cancer cell lines tested all showed significantly higher levels of MDM2 than hTERT-RPE1 cells." (PMID 39789219, 2025). "Response patterns to MDM2 inhibition vary significantly across cancer types." (PMID 41170373, 2025). "However, studies on human cancers have demonstrated that MDM2 is frequently modified and upregulated particularly in BC." (PMID 40308267, 2025). "However, overexpression & frequent activation of MDM2 are observed in many human cancers including hepatocellular carcinoma." (PMID 40339040, 2025). "Recent advances in developing E3 inhibitors, including MDM2 inhibitors, highlight their potential and ultimately guide the framework to establish E3 inhibition as effective strategies to treat specific types of cancers." (PMID 40002221, 2025).
cancer (continued). "Indeed, MDM2 inhibitors induced a mixture of apoptosis and growth arrest in cancer patients in clinical trials." (PMID 40649216, 2025). "Overexpression of MDM2 has been reported in several cancers, including RCC." (PMID 39857959, 2025). "DDLPS in particular serves as the prototypical model of MDM2-driven cancer." (PMID 41515979, 2025). "Furthermore, combination therapies targeting GPX4 and FAK/Src were found to enhance cancer cell death, and MDM2, ezrin, and cortactin were identified as potential ferroptosis inhibitor targets." (PMID 40164758, 2025). "HNK acting as a down-regulator of MDM2 and MDMX could be a potential anticancer agent in cancers with MDM2 overexpression." (PMID 41303693, 2025). "Our lab has been discovering and developing MDM2 inhibitors for cancer therapy." (PMID 39802403, 2025). "Functional polymorphisms in the MDM2 promoters have been linked to cancer risk and several non-malignant conditions." (PMID 39979836, 2025). "As a key oncogene, MDM2 promotes cancer cell proliferation and cell cycle progression." (PMID 41203626, 2025). "New approaches to neutralizing MDM2 in cancer are urgently needed." (PMID 40896364, 2025). "This review focuses on clinical trials evaluating MDM2 inhibition for cancer therapy." (PMID 41515979, 2025). "Additionally, MDM2 activates the protein kinase B (Akt) pathway through Akt phosphorylation, resulting in improved cancer cell survival and increased epithelial-mesenchymal transition." (PMID 41299419, 2025). "Therefore, small molecule stabilization of the 14-3-3σ/MDM2 protein–protein interaction (PPI) is a potential therapeutic strategy for the treatment of cancer." (PMID 38237679, 2024). "MDM2 isoforms contribute to cancer proteome diversity and support oncogenic transformation." (PMID 39769278, 2024). "MDM2 antagonists such as RG7388are regarded as promising agents to treat cancer." (PMID 38334409, 2024).
cancer (continued). "Multiple studies have shown that MDM2 inhibitors achieve a synergy with ICB in treating cancers." (PMID 39272927, 2024). "In addition to impacting cell viability, exposure to PM emitted from both ABS and PLA filaments increased levels of murine double minute clone 2 (MDM2), which is observed in different types of cancers and promotes genomic instability." (PMID 39071151, 2024). "A notable example is the RING‐type E3 ligase MDM2, which is overexpressed in many human cancers." (PMID 39329019, 2024). "Therefore, it was of interest for the PPTP/C to test the in vivo single agent activity of several BCL-2 family inhibitors and MDM2 inhibitors across its diverse panels of pediatric cancer PDX models." (PMID 39510293, 2024). "Therefore, in combination therapy, Nutlin-3 sensitizes many types of cancer cells but has less effect in patients with low MDM2 expression." (PMID 38741108, 2024). "Additionally, MDM2 acts as an oncogene, with its overexpression driving cancer progression by promoting cell proliferation and survival." (PMID 39498386, 2024). "This makes targeting MDM2 a promising direction for cancer treatment." (PMID 38741108, 2024). "In addition, MDM2 PROTAC degraders have received heightened attention in recent years with higher cancer therapeutic efficacy, and their safety needs further determination1066." (PMID 38763973, 2024). "Several MDM2 inhibitors are currently being evaluated clinically for cancer therapy." (PMID 38763973, 2024). "Moreover, in some cancer cell lines, the isoform can be strongly upregulated by nutlin-3a or by more advanced forms of MDM2 antagonists acting alone." (PMID 39062022, 2024). "Through mapping cancer type-specific in silico KMT2D GI networks, we revealed several SL candidates, namely NDUFB4, MDM2, TUBA1B, and WRN, that encode targets of existing and in-development therapeutics, making them potentially viable drug targets in cancers harbouring KMT2DLOF alterations." (PMID 39578878, 2024). "Notably, MDM2 and MDMX amplification has emerged as a potential biomarker associated with hyperprogression during immunotherapy across various cancer types." (PMID 38784022, 2024). "We identified three priority class A candidates—namely the SL interactors MDM2, TUBA1B (COAD/READ), and NDUFB5 (STAD) and the AL interactor CDK6 (in the pan-cancer dataset)—that encode targets of approved anticancer drugs or that are the focus of drug development efforts." (PMID 39578878, 2024).
cancer (continued). "Dual degrading of Mdm2/X may be therapeutically differentiated, especially in cancers that are MdmX upregulated." (PMID 38216578, 2024). "The MDM2 oncogene is overexpressed in various human cancers, including NB." (PMID 38601081, 2024). "In a recent comprehensive pan-cancer study examining MDM2/X amplification across 250 studies involving 30,118 patients, it was found that amplification of MDM2/X expression predicts a poor response to immunotherapy and is associated with shorter overall survival." (PMID 38784022, 2024). "Biologically, MDM2 inactivation abrogates TOP2β degradation, stabilizes TOP2βcc, and subsequently increases the number of TOP2β-concealed DSBs, resulting in the rapid death of cancer cells via the apoptotic process." (PMID 38263255, 2024). "Subsequently, to define whether endogenous RPS4X interacted with MDM2 in human cancer cells, we conducted a co-immunoprecipitation assay using HeLa cells." (PMID 39199272, 2024). "Thus, dysregulation of the MDM2 protein can not only induce cell proliferation, but also inhibit apoptosis, promoting cancer occurrence." (PMID 40777979, 2024). "This complex facilitates MDM2-mediated Slug degradation and inhibits cancer cell invasion." (PMID 39239548, 2024). "We, therefore, speculate that FOXO1 may act in a cancer-promoting manner in certain cancer cell types by activating MDM2 transcription." (PMID 38519029, 2024). "Interestingly, the anti-cancer effect of Sirt6 seems more apparent in interaction with Sirt1, inducing MDM2-dependent Sirt1 degradation or potentiating the DNA damage response." (PMID 38254877, 2024). "Onco-Lnc explored 127 cancer samples with high and low expression of MDM2 gene." (PMID 37049742, 2023). "As strengths, we show an easy, cheap synthetic protocol to generate a novel chalcone that has strong cytotoxicity and selectivity in vitro against different types of cancers, has low toxicity in vivo, and has good pharmacokinetic properties with a possible binding capability to MDM2 protein." (PMID 37371806, 2023).